SDHB (succinate dehydrogenase complex iron sulfur subunit B)
Diseases named in the same sentence as SDHB in open-access papers (continued):
Sharing a sentence is not in itself a finding about the gene and the disease.
tumor (continued). "A transcriptomic analysis of 76 inherited and sporadic PPGLs identified 2 tumour clusters, one including SDHB, SDHD and VHL-mutated tumours (pseudohypoxic signalling cluster), and one comprising RET and NF1-mutated (kinase signalling cluster) tumours." (PMID 35938916, 2022). "In the SDHB branch, however, only sample P313 formed a discrete subcluster, whereas the tumor cells of other SDHB patients formed mixed subclusters." (PMID 36046044, 2022). "Methylation analysis of both HLRCC and SDHB-RCC tumors identified a CpG island methylator phenotype (CIMP) in both tumor types that demonstrated a degree overlap in the probes that were hypermethylated." (PMID 36455002, 2022). "SDH-deficient RCC is a subtype of RCC characterized by loss of immunohistological expression of SDHB, which was added to the WHO tumor classification in 2016." (PMID 36011051, 2022). "Logistic regression analysis revealed that RET-PCPG tumor cells are transcriptionally more similar to developed adrenal chromaffins, whereas SDHB-PCPG tumor cells appear to be in an earlier phase of adrenal development." (PMID 36046044, 2022). "Apart from a few exceptions (RET-PCPG P66) we found different iCNV patterns in chr13 and chr15 in a subset of the tumor cells; in P227 (SDHB-PCPG) we identified small variations in chr3 and chr17 but observed few intra-individual heterogeneities." (PMID 36046044, 2022). "The tumor was 1.8 cm in the greatest dimension, but 5 of the 6 SDHB-RCC tumors fell within a size range of 1.5–2.2 cm." (PMID 36455002, 2022). "The locus contains numerous cancer-associated genes (CASP9, SDHB, and others), including chromodomain helicase DNA binding domain 5 (the CHD5 gene), which was recently identified as a tumor suppressor in vivo." (PMID 34205964, 2021). "We analysed protein levels of respiratory chain complexes, including SDHB in six tumours with a comparable tumour cell content." (PMID 34822422, 2021). "Immunohistochemistry and molecular analysis of the wtGISTs revealed loss of SDHB expression and loss of the wild-type SDHA allele in tumour material." (PMID 33854214, 2021). "This small cohort was particularly enriched for patients with tumours of the carotid body (CBP) and cervical sympathetic chain (SCP) as well as those with pathogenic SDHB mutations." (PMID 34277980, 2021). "For instance, patients with SDHB mutations are highly predisposed to metastatic PPGL and are at risk of developing multiple tumours, which can be widely distributed from the skull base to the pelvic floor." (PMID 34021277, 2021). "This phenotype seems to be involved in tumor progression and mutations in the FH, SLC25A11, and MDH2 genes along with SDHB and SDHD mutations can be considered to be a risk factor for PPGL malignancy." (PMID 34833055, 2021). "A prominent example is the drop in the tumor suppressor succinate dehydrogenase (SDHA and SDHB) with the increasing tumor size." (PMID 33924061, 2021). "Different combinations of these genes should be tested depending on the availability of a tumor sample or the performance of SDHB-immunohistochemistry (SDHB-IHC)." (PMID 33081307, 2020). "Under metabolic stress conditions, particularly nutrient-poor and hypoxic conditions, SDHB regulation with Hsp90/TRAP1-directed protein folding produces sufficient energy to meet the energy metabolism requirements of tumor cells." (PMID 33575209, 2020). "Of these tumours, SDH-deficient (characterized by the loss of SDHB) and quadruple WT GIST (KIT/PDGFRA/SDH/RAS-P WT) subgroups were reported to display a marked overexpression of FGF4, identifying a putative common therapeutic target for the first time." (PMID 33199729, 2020). "SDHB-mutated PPGs activate the process of epithelial-to-mesenchymal transition (EMT), which plays a vital role in tumor metastasis." (PMID 32190664, 2020).
tumor (continued). "A recent retrospective study showed that, in 12 MPP patients with SDHB gene mutation, all patients had tumor reduction (12–100% by RECIST) upon CVD, which suggests CVD therapy probably works better in patients with SDHB mutation." (PMID 32132978, 2020). "Collectively, this study estimated that ~ 11% of PPGL patients carry germline mutations in the four genes (SDHA, SDHB, SDHC, SDHD; SDHx) encoding SDH subunits, and ~ 5% of PPGL patients have tumor DNA carrying the novel MAML3 translocation." (PMID 31234811, 2019). "The SDH (succinate dehydrogenase) respiratory complex with a role in the Krebs cycle and oxidative phosphorylation has four subunits encoded by 4 SDHx genes-SDHA, SDHB, SDHC, and SDHD that act as tumor suppressors." (PMID 30854332, 2019). "Accordingly, a loss of SDHB function can be observed in many tumor entities and during PDAC progression a reduction in SDHB expression has been described, too." (PMID 31877753, 2019). "Olaparib, an FDA-proved PARP inhibitor, markedly potentiates the therapeutic effect of TMZ in SDHB-mutant preclinical models; this occurs via induction of DNA lesions and inhibition of tumor growth in vitro and in vivo." (PMID 30925729, 2019). "The SDH complex consists of four subunits (SDHA, SDHB, SDHC, and SDHD), and a deficiency of this enzyme is known to activate tumor formation through dysregulation of HIF activity." (PMID 31817761, 2019). "In all, 81 cases (90%) of CNS tumors showed positive staining for SDHB in the whole tumor, and 6 cases (6.7%) revealed strong granular SDHB immunoreactivity in part of the tumor area." (PMID 30971719, 2019). "Additional testing included normal tumour tissue SDHA/SDHB immunohistochemistry and a normal g-banded karyotype to exclude a translocation involving chromosome 3." (PMID 31795919, 2019). "Biallelic inactivation of one of the four SDH subunit genes (SDHA, SDHB, SDHC, SDHD) is the most common mechanism causing SDH deficient (dSDH) tumours." (PMID 31308404, 2019). "To assess the clinical relevance of our findings, we inspected tumor tissue from paraganglioma patients with SDHA and SDHB mutations, as well as sporadic paraganglioma patients." (PMID 29880867, 2018). "Increased levels of succinate in tumour samples from PPGL patients have been confirmed in a number of studies and high succinate to fumarate ratios suggested as a metabolic marker for the detection of SDHB/SDHD-related PPGL tumours." (PMID 29450727, 2018). "A higher mRNA expression of the HIF1 (but not HIF2) target genes, GLUT1 and HK2, was reported in VHL-mutated compared to SDHB-mutated adrenal medulla tissue, and VHL-mutated tumours demonstrate increased glycolysis in comparison to SDHx-derived PPGL." (PMID 29450727, 2018). "In mouse xenograft models, subcutaneous implantation and tail vein injection with SDHB knockdown cells resulted in a larger tumor volume and accelerated cancer metastasis, respectively." (PMID 29449614, 2018). "Our study demonstrated that decreased SDHB expression (40.6%) in human HCC was correlated with tumor differentiation, stage (borderline) and overall survival." (PMID 29449614, 2018). "The SDHB-knockdown cells showed increased tumor formation and volume, as well as accelerated cancer cell metastasis compared with the mock- and vector-transfected cells." (PMID 29449614, 2018). "By contrast, the higher number of genetic abnormalities required for tumor initiation and maintenance in SDHB PPGL result in a lower penetrance of PGL, but when cells give rise to metastases they are assumed to be better adapted to sustain survival." (PMID 30106970, 2018). "Loss of heterozygosity in these PCPG individuals was frequently observed (77% of SDHB germline carriers), consistent with SDHB acting via a tumor suppressor mechanism." (PMID 30217226, 2018). "In SDHB-related syndrome, PPGL maintenance seems to be reduced compared to SDHD (p = 0.04 vs 0.95) due to higher probability of tumor cell regression in SDHB vs SDHD (p = 0.87 vs 0.00)." (PMID 30106970, 2018).
tumor (continued). "In 96 tumor specimens, 39 (40.6%) cases had low SDHB and 57 (59.4%) high SDHB expression in cancerous tissues." (PMID 29449614, 2018). "Patient exhibiting low SDHB expression had poor disease-free and overall survival compared with those with high SDHB expression in tumor tissues by Kaplan-Meier analyses." (PMID 29449614, 2018). "Previous studies indicated the loss of SDHB being a driver event by disturbing tumor metabolic environment Besides SDHB, we also found some other sporadic events involving known tumor drivers." (PMID 28358873, 2017). "SDHB loss-of-function mutations lead to mitochondrial enzyme SDH dysfunction, TGF-β signaling activation, and inflammation and are associated with tumor formation." (PMID 29116164, 2017). "The authors also identified a missense variation in the SDHD gene (p.G12S), and IHC for the SDHB subunit showed faint and focal staining in the tumor tissue as compared to endothelial cells serving as internal controls." (PMID 28768491, 2017). "Of interest, one of the genes that was commonly upregulated is succinate dehydrogenase B (SDHB), a tumor suppressor gene and respiratory enzyme." (PMID 26871475, 2016). "Gene array analysis revealed few genes commonly upregulated by both compounds, including succinate dehydrogenase b (SDHB), which is involved in respiration and is a known tumor suppressor gene." (PMID 26871475, 2016). "Using a proteomics screen, we now show that the mitochondrial unfoldase-peptidase complex ClpXP associates with the oncoprotein survivin and the respiratory chain Complex II subunit succinate dehydrogenase B (SDHB) in mitochondria of tumor cells." (PMID 27389535, 2016). "Missense SDHx variants were identified in five of 37 pairs of samples (SDHB Ala3Gly n=2, Ser163Pro n=1, and SDHD His50Arg n=2), in both tumor and paired adjacent normal samples, confirming their germline origin." (PMID 25694510, 2015). "Patients with SDHC mutations are more likely to develop carotid body tumours, less likely to have multiple tumours than in SDHD mutated PGL, and have low malignant potential compared to SDHB-mutated PGL." (PMID 26273102, 2015). "HIF-1α, an essential factor in tumor progression, was up-regulated in SDHB-silenced cells with the activation of p-AMPKα and down-regulated in SDHB-overexpressed cancer cells with the decreased p-AMPKα." (PMID 25491408, 2014). "For PUMC, the expression of metabolism-related proteins, such as Glut-1 and SDHB, differs in the tumor or stroma depending on the clinical and histologic tumor subtype." (PMID 24387319, 2014). "This would be a requirement specific for SDHD, as tumor development in SDHB, SDHC and SDHA appear to follow a two-hit kinetics." (PMID 24465590, 2014). "For PUMC, the expression of metabolism-related proteins such as Glut-1 and SDHB is likely different in tumor or stroma depending on the clinical and histologic subtype." (PMID 24387319, 2014). "It was discovered that the level of p-ERK was increased in the SDHB-silenced cells compared to control, indicating that inhibition of SDHB expression promoted tumour cell growth through ERK pathway in SKOV3 and A2780 cells." (PMID 25491408, 2014). "We found variants in the five genes APC, BRCA1, RET, RNASEL, and STK11 that were linked to autosomal dominant forms of cancer or neoplasm as well as four complex risk variants in ELAC2, MSR1, AIP, and SDHB." (PMID 25333069, 2014). "Here, we provided the first time that SDHB silencing resulted in increased tumour cell proliferation, invasion, migration and decreased apoptosis." (PMID 25491408, 2014). "Tumor phenotypes according to the SDH status were SDHA(+)/SDHB(+) > SDHA(–)/SDHB(–) > SDHA(–)/SDHB(+) > SDHA(+)/SDHB(–) in order of frequency." (PMID 23888270, 2013). "The one SDHB-positive WT tumor expressed IGF1R at comparable levels to the mutant GISTs in the study." (PMID 23730622, 2013).
tumor (continued). "Five genes encoding subunits of the succinate dehydrogenase (SDH) complex (SdhA, SdhB, SdhC, and SdhD) and the enzyme that flavinates SdhA are the leading tumor suppressor genes in familial PGL." (PMID 23451094, 2013). "When comparing VHL- and SDHB-derived tumor tissues, in the latter we observed the expected decrease in complex II activity, but also an increase in complex III activity." (PMID 22859959, 2012). "The WT GIST associated with a germline SDHA mutation showed complete loss of both SDHA and SDHB protein, while the tumor with a somatic, heterozygous SDHA mutation showed significant decreased in SDHA immuno-expression, as well as complete loss of SDHB." (PMID 22974104, 2012). "Distribution of tumor site (primary vs. metastasis) and Ki-67 labeling index according to SDHB expression (percentage of positive tumor cells) and immunstaining intensity." (PMID 24213468, 2012). "We employed this model for a proteomics based approach to identify changes characteristic for tumor aggressiveness, which we then explored in a homogeneous set of human SDHB- and VHL-PHEOs/PGLs." (PMID 22859959, 2012). "It is also been shown that silencing SDHB expression induces tumor-like phenotypic traits in cell cultures, and that the loss of any subunit protein, especially B, leads to the loss of SDH expression due to destabilization of its complex." (PMID 24213468, 2012). "Multiple other genes encoding enzymes of the tricarboxylic (TCA) cycle are considered tumor suppressor genes including SDHB, SDHC, and SDHD (Succinate Dehydrogenase subunits B,C,D)." (PMID 21695080, 2011). "The other forms are mediated by mutations in the RET proto-oncogene and the NF1, SDHB, SDHC, or SDHD tumor suppressor genes." (PMID 19763184, 2009). "Tumours associated with SDHD mutation are rarely malignant, in contrast to those arisen from mutation of the SDHB gene." (PMID 19243216, 2009). "The significance of SDHB positivity in PHL remains unclear and may be associated with distinct tumor-driving mechanisms, metabolic states, or potential prognostic differences." (PMID 41333221, 2025). "The positive SDHB result in this case may offer specific insights into the tumor’s biological behavior and prognosis, warranting further investigation." (PMID 41333221, 2025). "Furthermore, multivariate analysis identified large tumor size (> 5.1 cm), presence of > 3 mitoses/10 HPF, and SDHB loss as being associated with lower metastasis-free survival." (PMID 40445576, 2025). "Additionally, in the multivariate analysis, larger tumor size (> 5.1 cm), the presence of > 3/10 HPF mitosis, and SDHB loss were associated with lower metastasis-free survival." (PMID 40445576, 2025). "Functional testing including the use of SDHB IHC and tumor and serum metabolomics may aid the interpretation of VUSs in SDHx genes in the future." (PMID 39927693, 2025). "SDHB positivity may indicate favorable tumor biology, but further studies are needed to validate its prognostic value." (PMID 41333221, 2025). "Typically, positive SDHB expression correlates with benign tumor behavior." (PMID 41333221, 2025). "The increased abundance of SOD2 and SDHB suggests an enhanced tumor-suppressing effect of ST1926." (PMID 40429796, 2025). "Similarly, succinate dehydrogenase complex iron sulfur subunit B (SDHB), another mitochondrial enzyme with tumor suppressor properties, showed increased levels after ST1926 treatment." (PMID 40429796, 2025). "The current absence of natural tumour development allows for the investigation of the trigger necessary for tumour initiation when a heterozygous SDHB pathogenic variant is already present." (PMID 39000369, 2024). "In this aspect, again, this model is a faithful and unique representation of the human SDHB carrier situation, as SDHx mutation carriers often have elevated succinate levels in the absence of tumours or other symptoms." (PMID 39000369, 2024).
tumor (continued). "Furthermore, the aim is to make a comprehensive analysis of known markers like immunohistochemical expressions of Ki67, S100, and SDHB, along with the tumor’s size and weight." (PMID 38667494, 2024). "Our laboratory recently performed a metabolomic analysis of SDHB_KD, SDHB-mutant human progenitor cells developed from hPheo1, a physiologically relevant PCC patient-derived cell line and discovered an overactive polyamine pathway subsequently fully validated in human PPGL SDHB-mutant tumor samples." (PMID 39337514, 2024). "According to 2021 ESMO Guidelines, a “high risk of metastases” can be established when any patient presents with one or more of the following criteria: (A) tumor size ≥ 5 cm; (B) any extra-adrenal PGL; (C) known SDHB germline mutation; or (D) plasma 3MT > 3 fold above the upper limit of normal." (PMID 38543140, 2024). "As expected, all A5 SDHB-mutant tumours clustered among C1A (SDHx) tumours by WTS." (PMID 38978571, 2024). "Somatic loss-of-heterozygosity (LOH) at 1p36.13 with or without somatic copy-loss was detected in all tumours and SDHB immunohistochemistry confirmed tumoural SDH-deficiency." (PMID 38978571, 2024). "The intracellular distribution of SDHB IHC staining may vary in tumor cells, leading to complexities or variations in the interpretation of IHC results." (PMID 38473309, 2024). "SDHB was positively expressed in tumor cells, suggesting no deleterious mutation in the SDHx genes and the presence of a stable succinate dehydrogenase complex." (PMID 38721148, 2024). "We speculated that the increase in the expression levels of ACO2 and SDHB is related to the decrease in ATP7B in tumor tissues." (PMID 39198750, 2024). "The authors show that the loss of CI occurs gradually over passages in SDHB KO cells, and that this loss is beneficial to CII-deficient cells by increasing their production of aspartate, their proliferation rate, and their capacity for tumor growth." (PMID 39335562, 2024). "Due to these clinical features, cluster-1 tumors are more frequently asymptomatic and especially SDHB-PGLs may reach a large tumor size at diagnosis." (PMID 39457697, 2024). "Additionally, it has been demonstrated that silencing SDHB expression induces tumor-like phenotypic traits in cell cultures." (PMID 39334573, 2024). "A further IHC staining of tyrosine hydroxylase (TH) and SDHB was negative, suggesting the tumor was nonfunctional PGL with SDHx mutation." (PMID 36945070, 2023). "Another recent study indicated that tumor cells in SDHA-deficient RCC showed negativity for both SDHA and SDHB, while RCC caused by defects in the SDHB, SDHC, or SDHD genes only showed negativity for SDHB." (PMID 37367052, 2023). "Thus, tumour-suppressive SNORA14A increases SDHB protein levels to prevent oncometabolite succinate accumulation in HB cells." (PMID 36717552, 2023). "The comparison of adjacent normal tissues to the tumor tissue in the same tissue sections of multiple patient samples revealed compelling evidence of decreased functional or flavinated SDHA in tumor tissue using SDHB levels as an indicator." (PMID 37945749, 2023). "For SDHB, tumours were mostly (6/8) pelvic or abdominal PGL, with only one PHEO and one HNPGL." (PMID 37434651, 2023). "Moreover, the subunits SDHB and SDHC are linked with a subset of tumours correlated with poor prognostic outcomes." (PMID 37887384, 2023). "Additionally, some DGC patients tested negative for CDH1/CTNNA1 gene but had pathogenic variants in related tumor susceptibility genes, such as BRCA2, ATM, SDHB, PRSS1, MSR1, STK11, and PALB2." (PMID 37393258, 2023). "Moreover, suppressing HIF-1α and/or HIF-2α inhibited the enhanced growth rates of tumor cells, resulting from SdhB suppression, suggesting that ROS production and the subsequent activation of HIF-α were responsible for SdhB-induced tumor formation." (PMID 36671435, 2022).